EIF3A (eukaryotic translation initiation factor 3 subunit A)
Diseases named in the same sentence as EIF3A in open-access papers (continued):
Sharing a sentence is not in itself a finding about the gene and the disease.
tumor (73 papers, 2000 to 2026). "eIF3a and DEGs mutations were found to be correlated to chemosensitivity of some anti-tumor drugs and vital signal pathways." (PMID 38589831, 2024). "eIF3a expression was also demonstrated to be associated with chemosensitivity to several anti-tumor drugs." (PMID 38589831, 2024). "eIF3a expression was also clarified to be associated with chemosensitivity to several anti-tumor drugs." (PMID 38589831, 2024). "In this study, we report one of these tumor-associated autoantibodies, anti-eukaryotic translation initiation factor 3 subunit A (EIF3A) autoantibody, designated as XC90, and its potential application as a diagnostic biomarker of human HCC." (PMID 31363116, 2019). "In this study, we identified anti-EIF3A autoantibody as a novel tumor-associated autoantibody biomarker in HCC model mouse as well as in human HCC patients." (PMID 31363116, 2019). "In vivo, eIF3a is found overexpressed in a range of tumor entities, where it was described in association with a rather contrastive clinical outcome." (PMID 22619676, 2012). "YTHDF3 is highly expressed in OX-resistant CRC tissues and recognizes the 5′-UTR of m6A-methylated RNAs associated with tumor resistance, and recruiting eukaryotic translation initiation factor 3 subunit A (eIF3A) to promote translation of drug-resistant genes." (PMID 37737134, 2023). "The diverse findings on eIF3a expression and associated clinical parameters are hypothesised to be highly dependent on tumor origin." (PMID 22619676, 2012). "However, our previous findings on eIF3a suggest that there may be an alternate mechanism where eIFs suppress translation of mRNAs encoding tumor suppressor and growth retardation proteins." (PMID 39413959, 2024). "Interestingly, it has been shown that eIF3a knockdown increases translation of a subset of mRNAs including those encoding DNA repair proteins, which may act as tumor suppressors." (PMID 39413959, 2024). "Rescue experiments showed that EIF3A overexpression partially reversed the tumor-suppressive effects of SLC25A5." (PMID 42196314, 2026). "Eukaryotic translation initiation factors promote tumor development, and EIF3A was identified as a significantly different protein in this study, which has been reported to delay tumor cell growth following gene knockdown." (PMID 40265010, 2025). "In this study, we first analyzed the expression levels of eIF3a in patient peripheral blood and tumor tissue as well as from CRC cell line data in online databases (GEO and CCLE)." (PMID 38782896, 2024). "Published studies have demonstrated that eIF3a impacted tumor development through regulating several biological processes, including cell proliferation, apoptosis, colony formation and migration." (PMID 38589831, 2024). "The eIF3a expression was examined in the peripheral blood and tumor tissues of CRC patients, as well as in CRC cell lines, utilizing publicly accessible datasets." (PMID 38782896, 2024). "The regulatory roles and molecular mechanisms of eIF3a on biological processes in tumor development need to be further clarified." (PMID 38589831, 2024). "This is substantiated by the fact that forced expression of eIF3a can largely rescue METTL16 KO-mediated anti-tumor phenotypes, including inhibition of tumor growth and liver CSC self-renewal." (PMID 38302992, 2024). "Compared with the sh-NC cell group, sh-eIF3a mice exhibited significantly slower tumor growth (p < 0.01), resulting in a significantly smaller tumor volume (p < .01)." (PMID 38782896, 2024). "To further investigate the effect of eIF3a on tumor growth, we established a SW620 cell line wherein eIF3a was stably silenced and then examined malignant behaviors." (PMID 38782896, 2024). "Further, we silenced eIF3a to explore its effect on tumor growth in a nude mouse tumor xenograft model." (PMID 38782896, 2024).
tumor (continued). "IHC staining of these sections showed significant reduction of eIF3a expression in the intestines of mice injected with eIF3a siRNAs, indicating that the reduced tumor production was likely due to eIF3a knockdown." (PMID 39413959, 2024). "Malignancy and tumor growth were significantly inhibited by silencing eIF3a, while overexpression promoted malignant behaviors, with a positive correlation between PI3K/AKT activation and eIF3a expression." (PMID 38782896, 2024). "Our study showed that knockdown of eIF3a reduced the CDK4 and CDK6 expression in DLBCL cells, suggesting that targeting eIF3a has a potential anti-tumor effect in DLBCL." (PMID 38589831, 2024). "In tumor tissues, the expression of eIF3a mRNA and protein was notably reduced in sh-eIF3a mice compared to those in the sh-NC group (p < .01)." (PMID 38782896, 2024). "Conversely, a positive association was found between tumor purity and the expression levels of YTHDC1, EIF3A and CYP17A1 (average PCC = 0.42)." (PMID 38171932, 2023). "In MrGPS, the three m6A regulators are all readers and previous studies have described that EIF3A is overexpressed in malignant tumor cells and promote tumor cell proliferation." (PMID 38171932, 2023). "More specifically, silencing eIF3a remarkably reduced the number of tumor metastasis nodules formed in the lung and liver." (PMID 35300416, 2022). "For the cell wound healing assay, silencing eIF3a robustly impaired the mobility of tumor cells, as indicated by the relative wound closure width." (PMID 35300416, 2022). "In consistent with our study, eIF3a knockdown has been reported to inhibit the proliferation of several types of tumour cells." (PMID 35187743, 2022). "To mechanically investigate the role of eIF3a in tumor progression, we first examined the impact of eIF3a knockdown on tumor cell proliferation by performing an EdU staining assay." (PMID 35300416, 2022). "With further research, we found that eIF3a suppression notably inhibited pseudopodia formation and cytoskeleton reorganization, both of which are essential properties necessary for tumor cell invasiveness." (PMID 35300416, 2022). "Consistently, the colony formation assay also revealed a positive regulatory role of eIF3a in tumor proliferation ability." (PMID 35300416, 2022). "All six mice in the control group underwent serious tumor metastasis, whereas only half of the mice in the eIF3a knockdown group developed distant metastasis." (PMID 35300416, 2022). "eIF3a is widely recognized as a proto-oncogene correlated with tumor prognosis, occurrence, metastasis, and therapeutic response." (PMID 35300416, 2022). "The results showed that eIF3a was significantly overexpressed in tumor tissues compared with adjacent normal tissues." (PMID 35300416, 2022). "Eukaryotic translation initiation factor 3a (eIF3a) plays a key role in tumour occurrence, prognosis and therapeutic response." (PMID 35187743, 2022). "As shown in the results, the tumour growth rate in the control group was faster than in the eIF3a‐silencing group, demonstrating that eIF3a promotes proliferation, which was consistent with previous findings." (PMID 35187743, 2022). "In conclusion, our results demonstrated a novel role of eIF3a in the acquisition of tumor invasiveness." (PMID 35300416, 2022). "Many researchers have reported an important role for eIF3a in the occurrence and development of tumors, and elevated eIF3a expression favors the maintenance of the tumor malignant phenotype." (PMID 34512348, 2021). "EIF3A had low expression in tumour tissues relative to normal tissues and paired ccRCC tissues, and the expression of EIF3A in ccRCC tissues was significantly lower than that in nontumour tissues." (PMID 34923969, 2021). "Further, YTHDF2 facilitates YAP mRNA decay via the AGO2 system in normal tissue, while YTHDF1 promoted YAP mRNA translation by interacting with eIF3a in tumor tissue." (PMID 32106857, 2020).
tumor (continued). "We have expected that EIF3A-specific autoantibodies would occur in human HCC patients as in tumor model mouse which showed similar characteristics to human HCC18–27." (PMID 31363116, 2019). "As shown by the evidences above, eIF3a is considered a tumor promoting factor because of its potential role in malignant transformation and the control of cell growth." (PMID 28074905, 2017). "In conclusion, our results demonstrated that miRNA-488 is a tumor suppressor miRNA that acts by targeting eIF3a." (PMID 28074905, 2017). "Overexpressing tumors respond better to platinum-based chemotherapy, suggesting eIF3a as a putative predictive as well as prognostic tumor marker in OSCC." (PMID 22619676, 2012). "eIF3a (p150, also known as p170) is the largest eIF3 subunit and is overexpressed in a variety of tumours when compared with normal control tissues." (PMID 11953842, 2002). "Previous studies found that eIF3a participated in many tumor development processes, such as maintaining the stem cell-like characteristics, mitochondrial dysfunction and glycolysis activation in tumor cells, which further contributed to cell cycle and proliferation." (PMID 38589831, 2024). "Besides, immune related pathways were also enriched, indicating that eIF3a possessed a potential relationship to tumor immunity in DLBCL." (PMID 38589831, 2024). "Previous studies showed that the stable suppression of eIF3a could increase cell doubling time and change cell sensitivity to various cycle regulators, indicating the pro-oncogenic role of eIF3a in tumor development." (PMID 38589831, 2024). "Moreover, eIF3a expression was found to be related to chemosensitivity of several anti-tumor drugs in DLBCL, including Vincristine and Wee1 inhibitor." (PMID 38589831, 2024). "According to the findings above, we speculated that eIF3a might played critical roles in immune response and regulation of tumor environment, and further validated it." (PMID 38589831, 2024). "Although the molecular mechanism of eIF3a action in oncogenesis remains elusive, it is tempting to speculate that eIF3a may suppress synthesis of tumor suppressor proteins at the level of mRNA translation." (PMID 39413959, 2024). "Based on the METTL16 CRISPR gene tiling scan structure and PPI models, we identified 6 regions (R1–R6) that might be essential for tumor cell survival and predicted to interact with eIF3a/b." (PMID 38302992, 2024). "Besides, showed the top 10 most significant relationship between eIF3a expression and prognosis in tumor patients." (PMID 38589831, 2024). "Moreover, 114 DEGs were identified in the two clusters based on eIF3a expression, which had a close linkage to cell cycle and tumor immune." (PMID 38589831, 2024). "In contrast, other research found that eIF3a could protect low-grade malignancies from progressing to high-grade types, suggesting the potential tumor-suppressive role of eIF3a." (PMID 38589831, 2024). "Furthermore, tumor eIF3a expression was lower in the sh-eIF3a group, as confirmed by IHC staining (p < .01)." (PMID 38782896, 2024). "High eIF3a expression was correlated with tumor metastasis and overall survival." (PMID 35300416, 2022). "However, when treated with irinotecan, tumours in eIF3a‐silencing group exhibited significant drug resistance." (PMID 35187743, 2022). "Additionally, using immunohistochemistry assays, we observed an increase in eIF3a protein levels in tumor tissues compared to adjacent normal tissues." (PMID 35300416, 2022). "In addition, we revealed a novel role of eIF3a in tumor acquisition of invasive properties, including abundant pseudopodia formation and cytoskeleton reconstruction, by translationally regulating the expression of Cdc42 and RhoA." (PMID 35300416, 2022). "Obviously, the tumor growth rate was notably inhibited by eIF3a knockdown." (PMID 35300416, 2022). "Altogether, these results suggested that pseudopodia formation may be a crucial mechanism involved in eIF3a-promoted tumor cell invasion." (PMID 35300416, 2022).
tumor (continued). "Finally, the relationship of EIF3A expression and infiltration of immune cells and marker gene expression in ccRCC was researched by Tumour Immune Estimation Resource (TIMER)." (PMID 34923969, 2021). "Interestingly, EIF3A was relatively downregulated in ccRCC and negatively correlated with the degree of malignancy of the tumour." (PMID 34923969, 2021). "Other elements of EIF3 complex as well as translational machinery such as EIF3B, EIF3C, EIF4A, EEF1A, and EEF2 were already revealed as components of tumor-associated exosomes, which implicates exosomal delivery of translational machinery including EIF3A can be involved in tumor propagation." (PMID 31363116, 2019). "Knocking down EIF3A decreased proliferation rate, and reduced invasion and tumor formation in mice." (PMID 29050215, 2017). "Due to NDRG1’s known tumor-suppressive activity, the impairment of cell motility and invasion potential by eIF3a over-expression may be due to the ability of eIF3a to up-regulate the expression of NDRG1." (PMID 23437357, 2013). "Therefore, beyond its role in protein synthesis, eIF3a is emerging as regulator in tumour pathogenesis and therapy response and, therefore, a potential tumor marker." (PMID 22619676, 2012). "Recently, a new group of eIF3a downstream targets that might have huge impact on tumor therapy decisions and introduce eIF3a as not only prognostic but also a predictive tumor marker that was discovered in the NER pathway." (PMID 22619676, 2012). "The regulation of tyrosinated α-tubulin could link eIF3a expression to tumor therapy via the chemotherapeutic Docetaxel." (PMID 22619676, 2012). "eIF3a might be a potent candidate as predictive tumor marker for evaluating sensitivity to platinum-based chemotherapy." (PMID 22619676, 2012). "In addition, function analysis revealed eIF3a had a close linkage to cell cycle and tumor immune." (PMID 38589831, 2024). "However, the role of eIF3a in tumor development is controversial." (PMID 38589831, 2024). "Moreover, eIF3a expression was also related to prognosis of tumor patients." (PMID 38589831, 2024). "Several RNA-binding proteins, such as eukaryotic translation initiation factor 3 subunit A and polyadenylate-binding protein 1, showed significant difference in other tumor comparisons as well, implying that protein synthesis may differ considerably in all three tumor morphological groups." (PMID 37069213, 2023). "Finally, we evaluated whether EIF3A expression correlated with the infiltration of immune cells and the expression of marker genes in ccRCC by Tumour Immune Estimation Resource (TIMER) and Gene Expression Profiling Interactive Analysis (GEPIA)." (PMID 34923969, 2021). "We thought these proteins bands can confer epitopes that induce tumor-associated anti-EIF3A antibody, although they are not intact but may be modified by phosphorylation or degradation." (PMID 31363116, 2019). "In contrast to EIF4E, EIF3A has been reported to be upregulated in various cancers but plays different roles in carcinogenesis: acts as tumor suppressor in squamous cell carcinomas and is correlated with better survival, and acts as tumor promoter in other epithelial carcinomas." (PMID 25658620, 2015). "Opposingly, we could not show any significant association of eIF3a expression with clinical stage (P = 0.948), tumor grade (P = 0.221), age (P = 0.452), sex (P = 0.055), and nodal status (P = 0.716)." (PMID 22619676, 2012). "To further its regulatory role in CRC development and progression, we generated stably eIF3a-silenced CRC cells and established a nude mouse tumor xenograft model." (PMID 38782896, 2024). "eIF3a was highly expressed in the peripheral blood of CRC patients (p < 0.01, log FC = 3.03) as well as in patient tumor tissues and CRC cell lines." (PMID 38782896, 2024).
tumor (continued). "To illuminate the expression level of eIF3a in DLBCL, we firstly compared eIF3a expression between DLBCL and healthy controls in GSE25638, and found obviously high expression of eIF3a mRNA in tumor tissue." (PMID 38589831, 2024). "Difference is found in the expression of EIF3A, EIF3B, EIF3D, EIF3F, EIF3H, EIF3J, and EIF3M in different tumor stages." (PMID 36051357, 2022). "Last, we also observed strong correlations between eIF3a and PPP2R1B expression between tumor tissues from HPA and TCGA databases, further supporting our findings in cells." (PMID 34512348, 2021). "Anti-EIF3A antibodies were detected in patients’ sera at all tumor stages (TNM stage I to IV) and sizes, even at initial tumor stages (TNM stage I) or in tumor burden of small sizes (T < 2)." (PMID 31363116, 2019). "Its target antigen was identified as eukaryotic translation initiation factor 3 subunit A (EIF3A) by proteomic analysis, and the elevated expression of EIF3A in HCC tissues of tumor model mice as well as human patients was shown." (PMID 31363116, 2019). "For example, miR-875-5p may inhibit tumor growth and metastasis in HCC by downregulating the expression of the initiation factor 3 subunit a (eIF3a)." (PMID 38800376, 2024). "Overall, these findings suggested that eIF3a might serve as a promising biomarker for prognostic evaluation in DLBCL patients, which needs to be validated in larger cohort of tumor patients." (PMID 38589831, 2024). "Subsequently, we investigated irinotecan‐induced tumour cell apoptosis in the presence of eIF3a silencing or not." (PMID 35187743, 2022). "In addition, a positive correlation between eIF3a and PPP2R1B expression was also observed in tumor samples from the Human Protein Atlas and TCGA databases." (PMID 34512348, 2021). "Tumor-secreting exosomes, although derived from minimal tumor burden, may deliver increased EIF3A antigen and display a neo-B cell epitope that is not displayed in normal exosomes, leading to produce autoantibody." (PMID 31363116, 2019).
infection (17 papers, 2014 to 2025). The state of being infected such as from the introduction of a foreign agent such as serum, vaccine, antigenic substance or organism. "The eIF3a-knockdown rat model was constructed by adeno-associated virus type-1 (AAV1) infection, PAH was evaluated according to hemodynamic alteration, right heart hypertrophy and histopathological changes in the lung tissue." (PMID 40346622, 2025). "We also found that polysome association of the mRNA encoding eukaryotic initiation factor 3 subunit A (eIF3a), increases after infection." (PMID 31226162, 2019). "In infected MDBK cells, expression of all assessed proteins were maintained following infection, with the exception of eIF3A decreasing at 48 hpi." (PMID 38421168, 2024). "For example, in our previous studies we found that aquareovirus NS38 (the GCRV nonstructural protein expressed in host cells as early as 3 h post infection) interacts with host translation initiation factor eIF3A for virus replication." (PMID 38029205, 2023). "For example, EIF3A regulates re-initiation after termination of uORF translation, and DDX3 facilitates translation of mRNAs with complex 5’UTR and promotes CoV2 infection." (PMID 38335237, 2024).
cardiovascular disease (1 paper, 2023). "EIF3A was found to directly bind with 5′ UTR of ATF4, a critical antagonizing factor of oxidative stress in cardiovascular disease, and regulated the protein expression of ATF4 in a m6A dependent-manner." (PMID 36743697, 2023).
neurodevelopmental disorder (1 paper, 2025). A behavioral and cognitive disorder with onset during the developmental period that involves impaired or aberrant development of intellectual, motor, or social functions. "Integrating the findings from our human cohort and zebrafish models, we propose that haploinsufficiency of either EIF3A or EIF3B causes an eIF3-related cardiovascular, craniofacial, and neurodevelopmental disorder." (PMID 41033306, 2025).